SNHG8 (small nucleolar RNA host gene 8)
Diseases named in the same sentence as SNHG8 in open-access papers (continued):
Sharing a sentence is not in itself a finding about the gene and the disease.
cancer (18 papers, 2017 to 2025). A tumor composed of atypical neoplastic, often pleomorphic cells that invade other tissues. "SNHG8 is a tumor-associated lncRNA upregulated in various tumor types, increasing the proliferation, migration, invasion, and metastasis of cancer cells." (PMID 35659362, 2022). "LncRNA SNHG8 (small nucleolar RNA host gene 8) is affiliated with the lncRNA class and associated with most cancers and diseases." (PMID 35067159, 2022). "Our result is consistent with others’ reports that SNHG8 is associated with the progression in multiple types of cancer in the liver, colon, lung, ovary, prostate, esophagus, and so on." (PMID 34722282, 2021). "For example, SNHG8, located on 4q26 and encoding small nucleolar RNAs (snoRNAs), was detected in multiple malignant tumors, including non-small-cell lung cancer, hepatocellular carcinoma, and pancreatic adenocarcinoma." (PMID 34722282, 2021). "SNHG8 was overexpressed in different types of cancer, suggesting its role in the progression of these tumors." (PMID 35027621, 2022). "Small nucleolar RNA host gene 8 (SNHG8) is an oncogenic factor involved in many types of cancer and is considered a promising target for cancer therapy." (PMID 35832170, 2022). "LncRNA SNHG8 (small nucleolar RNA host gene 8) has been reported to participate in most cancers development." (PMID 35067159, 2022). "The risk signature of our study included 8 lncRNAs (CRNDE, LINC00844, FAM66C, TUBA3FP, SNHG8, HAR1A, LINC00641, and MYCNOS), and previous evidence has suggested that these lncRNAs are closely linked to the occurrence and development of cancer." (PMID 35832170, 2022). "SNHG8, is a member of the SNHGs (small nucleolar RNA host genes) family, was clarified as a critical driving force for the development of cancer." (PMID 35438133, 2022). "While previous studies on lncRNA SNHG8 mainly focused on cancer, this study is the first to investigate the regulatory role of SNHG8 in a HG-induced pHUVEC injury model and provide a theoretical basis for determining and screening new therapeutic targets for diabetic vascular disease." (PMID 38110485, 2023). "It has been basically agreed that SNHG8 can promote the progression of cancer." (PMID 35067159, 2022). "SNHG8 exerts oncogenic functions in the progression of many cancers." (PMID 34362407, 2021). "ZFAS1 and GAS5, but not SNHG5 and SNHG8 were significantly upregulated in cancer tissues in HCC patients." (PMID 34072570, 2021).
tumor (13 papers, 2018 to 2025). "Higher expression of SNHG8 was associated with tumor differentiation and clinical stage." (PMID 33330110, 2020). "Mechanically, SNHG8 counteracts the tumour‐suppressive effects of miR‐149 in HCC cells by acting as a sponge for miR‐149‐5P." (PMID 34907642, 2022). "In non-tumor diseases, upregulated SNHG8 serves as a competitive endogenous RNA by sponging miR‐425‐5p, and inhibits the SIRT1/NF‐κB signaling pathway to attenuate the ischemia-induced microglial inflammatory response." (PMID 35659362, 2022). "The results suggested that the expression of SNHG8 was positively correlated with tumor size and poor prognosis in EBVaGC." (PMID 34722282, 2021). "In univariate analysis, advanced tumor stage/pathological stage/histological grade, metastasis, increased SNHG3/SNHG4 expression and decreased SNHG5/SNHG8 expression were potential risk factors of shorter OS." (PMID 32126023, 2020). "For instance, SNHG5 is a tumor suppressor in GC, SNHG8 predicts a poor prognosis in GC patients and SNHG17 induces the development of GC." (PMID 31808752, 2019). "We also found that knockdown of SNHG8 suppressed tumor growth in vivo." (PMID 29736176, 2018). "SNHG8 knockdown inhibited tumor growth significantly after 28 days." (PMID 29736176, 2018). "SNHG8 modulates autophagy and apoptosis via the AKT/AMPK/mTOR pathway, suppressing tumor progression." (PMID 41301542, 2025). "In TNBC, SNHG22 drives tumor progression by sponging miR-324-3p and upregulating SUDS382; LRRC75A-AS1 (SNHG29) promotes tumor progression by targeting the miR-380-3p/BAALC pathway, and SNHG8 promotes tumor progression through the miR-335-5p/PYGO2 axis." (PMID 41301542, 2025). "The expression level of SNHG8 is significantly increased in HCC compared with the adjacent normal tissues, which provides an independent prognostic factor for tumour recurrence in HCC patients." (PMID 34907642, 2022). "Based on these results, lncRNA SNHG8 promotes HCC tumorigenesis and invasion via sponging miR‐149 and acts as a prognostic factor of tumour recurrence in HCC patients." (PMID 34907642, 2022). "Additionally, MeRIP-qPCR assays validated that SOCAR and SNHG8 transcripts were hypermethylated, and PCAT19 and COLCA1 transcripts were hypomethylated in LUAD tumor tissues." (PMID 37029420, 2023). "In the same matched tumor and adjacent non-tumor tissue, we detected no change in the expression of the SNORA24 host gene, SNHG8 (Small Nucleolar RNA Host Gene 8)." (PMID 31478838, 2019).
SNHG8 also shares sentences with these, for which no sentence is quoted: cervical cancer (2 papers); liver cancer (2); melanoma (2); prostate carcinoma (2); acute myocardial infarction (1); childhood asthma (1); COVID-19 (1); diffuse large B-cell lymphoma (1); ischemic stroke (1); Parkinson disease (1); progressive supranuclear palsy (1); rectal adenocarcinoma (1).